ZNF892 (zinc finger protein 892)
Description:
May be involved in transcriptional regulation.
Gene: Protein-coding gene on chromosome 2 (95,207,521 to 95,259,774, forward strand). Ensembl gene ENSG00000233757.
Subcellular location: Nucleus
Gene Ontology:
Molecular function: DNA-binding transcription factor activity, RNA polymerase II-specific; RNA polymerase II cis-regulatory region sequence-specific DNA binding; DNA-binding transcription repressor activity, RNA polymerase II-specific; sequence-specific DNA binding
Biological process: regulation of transcription by RNA polymerase II; negative regulation of transcription by RNA polymerase II; regulation of DNA-templated transcription
Cellular component: nucleus; nucleoplasm
Homologues: Orthologues: chimpanzee ZNF892 (99% identical), macaque ZNF892 (96% identical), dog ZNF892 (89% identical), pig ZNF892 (87% identical), rabbit ZNF892 (81% identical), rat Zfp418l1 (39% identical), tropical clawed frog znf883l (35% identical), mouse Zfp772 (29% identical), mouse Zfp773 (27% identical), mouse Zfp954 (26% identical). Paralogues in human: ZNF879 (46% identical), ZNF429 (46% identical), ZNF658 (45% identical), ZNF471 (45% identical), ZNF726 (44% identical), ZFP28 (44% identical), ZNF568 (44% identical), ZNF681 (44% identical), ZNF708 (44% identical), ZNF7 (43% identical), ZNF16 (43% identical), ZNF724 (43% identical), and 164 more.